TAF15 (TATA-box binding protein associated factor 15)
Diseases named in the same sentence as TAF15 in open-access papers (continued):
Sharing a sentence is not in itself a finding about the gene and the disease.
cancer (29 papers, 2008 to 2026). A tumor composed of atypical neoplastic, often pleomorphic cells that invade other tissues. "Chromosomal rearrangements involving FUS, EWSR1, or TAF15 drive multiple cancers, and mutations in the genes encoding the FET proteins are associated with neurodegenerative disease." (PMID 42051291, 2026). "The strong nuclear preference of EWS in most cell types in contrast to FUS and TAF15 may be connected to its more frequent mutation in human cancers were the oncoprotein is restricted to nuclear functions as an aberrant transcription factor." (PMID 18620564, 2008). "In this work, we demonstrated that several well-characterized IDRs including those from FUS, EWS and TAF15, promote the condensation of CARs on the T cell membranes, which leads to enhanced cytotoxicity toward low-antigen-expressing cancer cells." (PMID 41023404, 2025). "Accumulating studies have shown that TAF15 is involved in the processes of human cancers, including extraskeletal myxoid sarcomas, leukaemia, human neuroblastoma, and lung squamous cell carcinoma." (PMID 37037864, 2023). "The results indicated that the mRNA expression levels of TAF15 were significantly upregulated in 12 cancer types and downregulated in 3 cancer types." (PMID 37037864, 2023). "TAF15 plays an important role in regulating mRNA transcription, RNA splicing, and transportation in cancer and other diseases." (PMID 36895010, 2023). "First, the TAF15 expression level was analyzed from a pan-cancer perspective on the basis of TCGA and TIMER databases." (PMID 37037864, 2023). "One family with essential functions in RNA processing in cancer and NDs is the FET family of proteins, consisting of FUS, EWSR1, and TATA-Box Binding Protein Associated Factor 15 (TAF15)." (PMID 35731869, 2022). "Abnormally formed FUS/EWS/TAF15 (FET) fusion oncoproteins are essential oncogenic drivers in many human cancers." (PMID 33674598, 2021). "In combination with radiation, the anti-TAF15 antibody led to a reduction in the surviving fraction of cancer cells." (PMID 32676166, 2020). "Inhibition of TAF15 showed a growth-inhibitory effect and resulted in increased apoptosis and decreased proliferation in cancer cells." (PMID 32676166, 2020). "We found that the antibody targeting TAF15 enhances the cytotoxicity of cancer following irradiation." (PMID 32676166, 2020). "Previously, we discovered TAF15 as a radiation-inducible lung cancer surface protein by the use of phage-displayed peptide libraries." (PMID 32676166, 2020). "Radiation-induced surface expression of TAF15 will facilitate selective targeting of cancer by therapeutic antibodies and minimizing normal lung toxicity." (PMID 32676166, 2020). "The biodistribution of the anti-TAF15 antibody throughout cancer sections demonstrates potential bioavailability in tumor therapy." (PMID 32676166, 2020). "We targeted TAF15 with a blocking antibody to determine the feasibility of developing a molecular target for the treatment of cancer." (PMID 32676166, 2020). "Enhanced binding of the anti-TAF15 antibody was observed in both cancer models following irradiation." (PMID 32676166, 2020). "Although the therapeutic effect of PAT-BA4 has been limited in vitro, TAF15 targeting therapy has demonstrated anti-adhesion and anti-migration effects in cancer cells, which indicates the importance of TAF15 for increased malignant potential." (PMID 27181033, 2016). "Of the many RBPs that bind to the KRAS 3′ UTR, AGO2, HuR (or ELAVL1), IGF2BP1/2/3, PUM2, EWSR1, TAF15, FUS, and TIA1 have been previously implicated in cancer." (PMID 26930719, 2016). "The FET family proteins (FUS, EWSR1 and TAF15) are abundant and highly conserved RBPs involved in cancer biology and other diseases." (PMID 24714572, 2014). "For example, AGO protein is an RBP that serves as a platform of mRNA and small RNA interactions, and the FET family RBPs, including FUS, EWSR1 and TAF15, play important roles in RNA editing and human cancers." (PMID 24714572, 2014).
cancer (continued). "More importantly, we validated the role of TAF15 in the TET family of RNA-binding proteins in circDNA and tumor development, which may also be associated with cancer and drug resistance." (PMID 36895010, 2023). "TAF15 is a radiation-inducible molecular target for the development of anti-cancer antibodies." (PMID 32676166, 2020). "Furthermore, the microscopic biodistribution revealed that the anti-TAF15 antibody distributed throughout cancer." (PMID 32676166, 2020). "To determine if the expression of TAF15 associated with overall survival (OS) in NSCLC patients, we analyzed the RNA-Seq data for cancer (Cancer Genome Atlas (TCGA)) and healthy tissue (Genotype-Tissue Expression (GTEx)) using the web-based Gene Expression Profiling Interactive Analysis (GEPIA)." (PMID 32676166, 2020). "Moreover, cancer-specific binding of an anti-TAF15 antibody labeled with near-infrared dye was found during whole-animal imaging." (PMID 32676166, 2020). "We hypothesized that TAF15 induction following radiation might lead to enhanced cancer cell survival." (PMID 32676166, 2020). "However, the interaction between circRNAs and TAF15 in cancers is rarely reported." (PMID 36895010, 2023). "The methylation on many of arginine methylation sites identified in cultured cells was present in cancer cell samples, such as those on KRT1 and TAF15 proteins, further strengthening the functional importance of PRMT-mediated arginine methylation in cancers." (PMID 33782401, 2021). "Depletion of two SAM downregulated genes STMN1 and TAF15 reduces cellular transformation and invasiveness, providing evidence that SAM targets are genes important for cancer growth and invasiveness." (PMID 29340097, 2017). "Both TAF15 and LINC00665 were downregulated in glioma carcinoma tissues and cancer cells." (PMID 35563845, 2022). "Since no significant expression changes of TAF15 existed between the cancer and normal tissues of CRC, probably MYBL2 dominated the S-phase RRM2 transcription in the complex in CRC cells." (PMID 34234118, 2021). "Therefore, post-treatment cancer relapse may occur through non-distinct subpopulations and may be effectively prevented by α-amanitin to disrupt transcriptional machinery, including TAF15." (PMID 27181033, 2016).
tumor (19 papers, 2016 to 2026). "Overexpression of TAF15 was associated with a larger tumour size, high pathologic stage and high T stage of GC." (PMID 37037864, 2023). "Crucially, TAF15 silencing abolishes the tumor-suppressive functions of type I/III ROP16, establishing TAF15 as a key mediator in ROP16-induced oncosuppression." (PMID 40684184, 2025). "During the new trial, we observed that FUS and TAF15 slowed tumor progression, which is consistent with the result from previous experiments." (PMID 41023404, 2025). "We silenced TAF15 in A549 cells overexpressing type I, II and III ROP16 to examine its impact on ROP16-mediated anti-tumor functions, thereby exploring potential mechanisms underlying these effects." (PMID 40684184, 2025). "EWS and TAF15 promoted tumor killing in some models and their ineffectiveness in other models can be explained by a reduction in CAR expression or hyperactive signaling-induced loss of function." (PMID 41023404, 2025). "We found that FUS and TAF15 CAR-T inhibited tumor growth better than the control CAR-T, which is consistent with the in vitro killing results." (PMID 41023404, 2025). "TAF15 knockdown suppressed the proliferation, migration and invasion of GC cells in vitro and inhibited the tumour growth in vivo." (PMID 37037864, 2023). "TATA-box-binding protein-associated Factor 15 (TAF15), a member of the FUS/EWS/TAF15 (FET) family, contributes to the progression of various tumours." (PMID 37037864, 2023). "The molecular hallmark of this tumor, present in over 90% of cases, is the fusion of NR4A3 with EWSR1 at 22q12.2 or TAF15 at 17q12." (PMID 37484580, 2023). "The results demonstrated that knockdown of TAF15 significantly inhibited tumour growth and tumour weight." (PMID 37037864, 2023). "Based on the results of IHC analysis, we found that overexpression of TAF15 was positively related to tumour size, T stage and pathologic stage." (PMID 37037864, 2023). "In this study, we found that TAF15 was significantly upregulated in GC tumour tissues and cell lines." (PMID 37037864, 2023). "An increasing number of studies have described that TAF15 is also involved in the cellular stress response, cell spreading and cell adhesion, which are well known to play a crucial role in tumour cell migration and invasion." (PMID 37037864, 2023). "In particular, TAF15 and S100B resulted the most promising biomarkers for the discrimination between control and tumor." (PMID 33469081, 2021). "After excluding general RNA-binding proteins, four potential tumor progression-related proteins (TAF15, HNRPK, NKRF and PTBP3) were identified." (PMID 32393270, 2020). "We next evaluated TAF15 expression in NSCLC patients using a tumor tissue microarray (TMA) containing NSCLC and matched healthy lung tissue." (PMID 32676166, 2020). "Similarly, our study verified that TAF15 knockdown suppressed the proliferation, migration and invasion of GC cells in vitro and inhibited tumour growth in vivo." (PMID 37037864, 2023). "Introduction of tumour mutations at the gene’s 5′ end impacted protein binding, including a significant loss of interaction with the RNA Polymerase II complex mediated by known NEAT1 interactor TAF15." (PMID 37291246, 2023). "Furthermore, we identified the level of TAF15 in all xenograft tumours using western blotting analysis." (PMID 37037864, 2023). "TAF15 and S100B, were the best biomarkers to differentiate the tumor from the non-tumor conditions." (PMID 33469081, 2021). "TAF15 was statistically more abundant in non-tumor samples, as compared to the tumor group." (PMID 33469081, 2021). "Here, TAF15 was statistically more abundant in non-tumor group." (PMID 33469081, 2021). "In summary, TAF15 was found to be overexpressed in GC tumour tissues and cells and to contribute to GC malignant progression via the RAF1/MEK/ERK signalling pathway, which suggests that TAF15 might be a potential molecular diagnostic marker or therapeutic target for GC." (PMID 37037864, 2023).
tumor (continued). "In summary, TAF15 is overexpressed in GC tumour tissues and cell lines, and promotes cell proliferation, migration and invasion in GC via the RAF1/MEK/ERK signaling pathway, which suggests that TAF15 might be a potential molecular diagnostic marker or therapeutic target for GC." (PMID 37037864, 2023). "By isolating tumor-infiltrating T cells, we found that the FUS and TAF15 group showed an increased number of tumor-infiltrating T cells, although the T cell numbers in blood were comparable across the control, FUS and TAF15 groups." (PMID 41023404, 2025). "GMDS-AS1 stabilizes SIRT1 mRNA by recruiting TAF15, leading to p65 deacetylation and reduced MMP-9 expression, acting as a tumor suppressor in LUAD." (PMID 40684184, 2025). "Our data first showed that TAF15 knockdown led to a significant decrease in the phosphorylation levels of RAF1, MEK and ERK1/2, while total RAF1, MEK and ERK1/2 exhibited no significant change in GC cell lines and xenograft tumours." (PMID 37037864, 2023).
neurodegenerative disease (17 papers, 2015 to 2026). A disorder of the central nervous system characterized by gradual and progressive loss of neural tissue and neurologic function. "The presence of abundant TAF15 amyloid filaments with a characteristic fold in FTLD establishes TAF15 as a member of the small group of proteins known to form neurodegenerative disease-associated amyloid filaments." (PMID 38057661, 2024). "This study provides structural and genetic evidence that TAF15 amyloid filaments underlie the diverse group of neurodegenerative diseases currently termed FTLD-FET, which we therefore rename FTLD-TAF15." (PMID 41648099, 2026). "Mutations in various RNA binding proteins such as hnRNP A1, hnRNP A2/B1, FET protein family (FUS, TAF-15, EWSR1) Matrin-3, TIA-1 and Ataxin-244 are implicated in various neurodegenerative diseases." (PMID 29070802, 2017). "This focuses attention on the role of TAF15 proteinopathy in neurodegenerative disease." (PMID 38057661, 2024). "In addition, aggregation-enhancing mutations in EWSR1 and TAF15 are associated with ALS, suggesting that changes in the biology of these proteins are sufficient to drive neurodegenerative disease." (PMID 30068389, 2018). "TAF15 is an RNA binding protein (RBP) and is reported to colocalize with tau pathology in neurodegenerative diseases." (PMID 32224504, 2020). "The suppression by TAF15 is specific to FUS and not found in other yeast models of neurodegenerative disease-associated proteins." (PMID 42187823, 2026). "We also present the complete list of human proteins with PrLDs and discuss the prevalence of the PrLD in nucleic-acid binding proteins that are often connected to neurodegenerative disease, including: ataxin 1, ataxin 2, FUS, TDP-43, TAF15, EWSR1, hnRNPA1, and hnRNPA2." (PMID 26996412, 2016). "However, it was not clear if TAF15 proteinopathy was more widespread in neurodegenerative diseases." (PMID 41648099, 2026).
neurological disease (4 papers, 2012 to 2024). "Among the proteins we found that were implicated in both the neurological disease and RNA processing pathway using IPA was TAF15." (PMID 39739690, 2024). "An example of TAF15 mRNA turnover target involved in transcriptional control and also neurological diseases is the CGG-binding protein 1 (CGGBP1), which binds to CGG repeats in the promoter of the fragile X mental retardation 1 (FMR1) gene resulting in reduced expression." (PMID 27378374, 2016). "The presented data support that FUS and TAF15 are more functionally related to each other, and that the FET-proteins have distinct functions in cellular signaling pathways which could have implications for the neurological disease pathogenesis." (PMID 23049996, 2012).
neuromuscular disease (1 paper, 2015). "This study, therefore, provides a platform for understanding mechanism of RNA recognition particularly by TAF15, and in general the FET family of proteins, which is likely to aid in understanding the molecular basis of neuromuscular disease progression." (PMID 26612539, 2015).
TAF15 also shares sentences with these, for which no sentence is quoted: Alzheimer disease (4 papers); melanoma (2); autoimmune uveitis (1); brain tumor (1); cognitive decline (1); colon cancer (1); extraskeletal myxoid chondrosarcoma (1); fibrosis (1); fragile X syndrome (1); glaucoma (1); metastatic tumours (1); myocardial infarction (1); myxoid liposarcoma (1); nasopharyngeal carcinoma (1); Obesity (1); ovarian tumor (1); Parkinson disease (1); spinal muscular atrophy (1); stomach cancer (1); uveitis (1).